EPHX2 (epoxide hydrolase 2)
Diseases named in the same sentence as EPHX2 in open-access papers (continued):
Sharing a sentence is not in itself a finding about the gene and the disease.
tumor (47 papers, 2013 to 2025). "Collectively, these data demonstrate that EPHX2 is a highly valuable tumor diagnostic biomarker across a wide range of tumor types, such as in CESC and KIRC." (PMID 40129060, 2025). "Beyond its implications on tumor biology, the association between EPHX2 expression and patient prognosis highlights its potential utility as a prognostic marker for ccRCC." (PMID 40538850, 2025). "Herein, multiple bioinformatics tools were used to comprehensively evaluate the expression, diagnostic, and prognostic significance of EPHX2 and its roles in the tumor immune microenvironment in human cancers." (PMID 40129060, 2025). "EPHX2 expression was significantly linked to immune cell infiltrations (particularly tumor‐associated macrophages), tumor mutation burden, microsatellite instability, immune modulators, and immunotherapeutic biomarkers." (PMID 40129060, 2025). "Our findings indicated that EPHX2 expression is inversely associated with several cancer‐related biological processes, including the cell cycle and apoptosis, thereby impeding tumor growth and progression." (PMID 40129060, 2025). "We found that anti-PD-1 up-regulated Ephx2, the pro-inflammatory gene encoding sEH, in multiple tumor types." (PMID 38330013, 2024). "This suggests that EPHX2‐associated immune infiltration in different tumors might have a complex interplay affecting tumor development and progression." (PMID 40129060, 2025). "Here, we demonstrate that ICI can increase Ephx2 expression, implicating a potential mechanism underlying immunotherapy failure and highlighting the need to further investigate sEH inhibitors as a novel adjuvant to improve the anti-tumor efficacy of ICI." (PMID 38330013, 2024). "However, when two expert pathologists, aided by DP, selected and analyzed only the tumor areas, we observed significant association between clinical data and EPHX2 expression, as presented in this study." (PMID 39125591, 2024). "Gene-expression levels of Ephx2, which encodes murine sEH, were increased in gemcitabine-induced debris-stimulated Panc02-H7 tumors compared to size-matched Panc02-H7 tumors derived from living tumor cells." (PMID 34607951, 2021). "IL10/EPHX2 double knockout mice also showed reduced IBD-associated tumor development." (PMID 31002701, 2019). "Thus, EPHX2 expression diminishes in many types of tumors as they grow, is diminished in tumor-associated endothelial cells, is suppressed in metastases, and is eliminated or reduced in several types of human cancers and frequently also in the adjoining normal tissue." (PMID 32398692, 2020). "Studies examining how EPHX2 influences tumor progression through lipid metabolism reprogramming remain limited." (PMID 40538850, 2025). "The results demonstrated a significant disparity in EPHX2 expression within ccRCC tissues relative to other tumor types, with normal tissues exhibiting higher expression levels." (PMID 40538850, 2025). "Initial assessments involved eight pairs of fresh tissue specimens from normal and ccRCC patients for qPCR and WB validation, revealing that both RNA and protein levels of EPHX2 were significantly reduced in tumor samples." (PMID 40538850, 2025). "The inverse relationship between diminished EPHX2 levels and advanced tumor stages accentuates the necessity for identifying molecular markers that can guide clinical decision-making and therapeutic strategies." (PMID 40538850, 2025). "Current evidence strongly suggests that EPHX2 is a valuable tumor biomarker in different tumors, such as in CESC and KIRC." (PMID 40129060, 2025). "Meanwhile, we investigated the correlation between EPHX2 expression and tumor pathological stages using the GEPIA2 tool." (PMID 40129060, 2025). "To further substantiate the differential expression of EPHX2 in ccRCC, we successfully constructed a data model representing the ccRCC tumor and normal groups, facilitating pairwise difference analysis via the TCGA database." (PMID 40538850, 2025).
tumor (continued). "By combining data from various studies on EPHX2 expression in tumor and normal tissues, we uncovered the immunotherapeutic potential of EPHX2 in a range of tumor types." (PMID 40129060, 2025). "To confirm the differential expression of EPHX2 between tumor and normal kidney tissues, we conducted quantitative PCR (qPCR), western blotting (WB), and histological microarray validations." (PMID 40538850, 2025). "The assessment of EPHX2 mutations, copy number alteration (CNA), and methylation conditions in pan‐cancer indicated that EPHX2 genomic modifications were higher than 20% in BLCA tumor samples, with “deep deletion” being the most common type." (PMID 40129060, 2025). "Our findings revealed a marked reduction in EPHX2 expression within tumor tissues, corroborated by data mining efforts and the analysis of human ccRCC tissue samples." (PMID 40538850, 2025). "Emerging articles have identified links between EPHX2 and clinical disorders, particularly neoplastic diseases." (PMID 40129060, 2025). "This research aimed to detail the prognostic landscape of EPHX2 in pan‐cancer and explore its potential relationship with immune infiltration in the tumor microenvironment." (PMID 40129060, 2025). "Studies have demonstrated that EPHX2 inhibits tumor progression in various cancers by regulating lipid metabolism, supporting its analogous role in ccRCC." (PMID 40538850, 2025). "In summary, EPHX2 was aberrantly expressed in various tumor types and exhibited a strong correlation with clinical progression and prognosis." (PMID 40129060, 2025). "We observed the effect of EPHX2 expression on tumor stages in COAD, KICH, KIRC, KIRP, LIHC, and PAAD (all p < 0.05), but not in others." (PMID 40129060, 2025). "Tumor tissues harvested from the anti-PD-1 treatment group exhibited a 2.5-fold increase in Ephx2 expression." (PMID 38330013, 2024). "Tumor tissue harvested from anti-PD-1-treated mice exhibited significantly higher levels of Ephx2 when compared to tumor tissue from vehicle-treated mice." (PMID 38330013, 2024). "The results showed that EPHX2 deletion accelerated primary tumor growth, increased tumor macrophage count, and angiogenesis." (PMID 39125591, 2024). "The identification of nuclear EPHX2 expression in primary BC tumor samples in the present study represents the first evidence of this phenomenon that warrants further investigation." (PMID 39125591, 2024). "Panigrahy and colleagues showed that CYP2CJ and CYP2C8 overexpressing mice and Ephx2-/- mice had enhanced corneal and neonatal retinal vascularization and enhanced tumor dependent corneal angiogenesis." (PMID 30792659, 2019). "Downregulation of EPHX2 may accelerate ccRCC progression by promoting a shift in lipid metabolism toward a state that favors tumor cell proliferation." (PMID 40538850, 2025). "In this view, targeting EPHX2‐dependent signaling could be a promising therapeutic strategy for tumor immunotherapy." (PMID 40129060, 2025). "Notably, EPHX2 expression was significantly lower in ccRCC tumor tissues compared to normal renal tissues (P < 0.001)." (PMID 40538850, 2025). "Furthermore, we found that EPHX2 expression was significantly correlated with tumor stage in COAD, KICH, KIRC, KIRP, LIHC, and PAAD." (PMID 40129060, 2025). "The observed downregulation of EPHX2 in tumor tissues correlates with aggressive tumor characteristics and unfavorable patient outcomes, underscoring the necessity for further exploration of its mechanistic pathways, particularly concerning the PI3K/AKT signaling pathway." (PMID 40538850, 2025). "Our findings revealed that EPHX2 was generally downregulated in most cancer types according to TIMER, TCGA, and GTEx datasets, implying that EPHX2 may exert a tumor‐suppressive effect." (PMID 40129060, 2025). "Additionally, gene set variation analysis (GSVA) was performed to elucidate the biological role of EPHX2 across 33 tumor types." (PMID 40129060, 2025).
tumor (continued). "EPHX2, a metabolic regulator with tumor-suppressive properties, not only influences cell cycle dynamics but also interacts with multiple signaling pathways to inhibit tumor growth." (PMID 40538850, 2025). "Prior studies have indicated that EPHX2 may possess tumor-suppressive qualities across various cancer types; however, its specific involvement in ccRCC is not yet fully elucidated." (PMID 40538850, 2025). "This suggests that EPHX2 expression may play a role in tumor progression and resistance to cell death." (PMID 40129060, 2025). "Downregulation of EPHX2 may promote malignant behaviors of tumor cells by affecting lipid signaling pathways, such as the phosphatidylinositol-3-kinase (PI3K)/protein kinase B (AKT) signaling pathway." (PMID 40538850, 2025). "Using DP, EPHX2 protein expression was evaluated solely in tumor areas." (PMID 39125591, 2024). "Likewise, EPHX2 expression negatively correlated with tumor size, estrogen receptors, and Ki67 expression." (PMID 39125591, 2024). "Our IHC analysis revealed cytosolic expression of EPHX2 protein in tumor cells." (PMID 39125591, 2024). "MAPKAPK2, MAOA, and EPHX2 were demonstrated to affect tumour development in various contexts." (PMID 36826154, 2023). "Subsequently, the same group demonstrated that dual inhibition of cyclooxygenase-2 and EPHX2 with celecoxib and t-AUCB, respectively, synergistically suppressed primary tumor growth and metastasis by inhibiting tumor angiogenesis." (PMID 39125591, 2024). "ALDH2, ADH1B, ALDH3A2, DPT, EPHX2, and GATM were down-regulated in the tumor tissues, which is consistent with the expression of hub genes in the GSE3189 and GSE46517 datasets." (PMID 38378847, 2024). "EPHX2 (-/-) /IL10(-/-) double knockout mice also displayed decreased precancerous dysplasia and tumor size, when compared to IL10(-/-) mice." (PMID 31002701, 2019). "While cytoplasmic expression of EPHX2 has been predominantly described in various tumor types, there have been no previous reports of nuclear expression in cancerous tissues." (PMID 39125591, 2024).
cancer (36 papers, 2013 to 2026). A tumor composed of atypical neoplastic, often pleomorphic cells that invade other tissues. "Both biomarkers (TMB and MSI) for immunotherapy were significantly associated with EPHX2 in certain cancers." (PMID 40129060, 2025). "The underlying EPHX2‐associated signaling pathways in cancers were investigated by gene set variation analysis (GSVA)." (PMID 40129060, 2025). "As expected, markers of liver differentiation, such as EPHX2, showed downregulation, while those associated with cancer proliferation, such as MKI67, increased." (PMID 39199347, 2024). "Consequently, EPHX2 holds potential as a diagnostic marker for identifying mutations, CNAs, and epigenetic alterations in cancer." (PMID 40129060, 2025). "EPHX2 was demonstrated to be strongly associated with cancer prognosis and macrophage phagocytosis." (PMID 37090691, 2023). "We conducted additional qPCR experiments to validate the gene expression levels of EPHX2 in various cancer cell lines, further substantiating its involvement in cancer." (PMID 40129060, 2025). "The ESTIMATE algorithm was applied to determine the immune and stroma scores for each sample in the TCGA database to evaluate the immunological features of EPHX2 in the TME from different cancer types." (PMID 40129060, 2025). "We examined EPHX2 expression across 33 human cancers and normal tissues utilizing the TCGA database." (PMID 40538850, 2025). "We initially undertook a systematic bioinformatic analysis of the molecular landscape of the EPHX2 gene in pan‐cancer using multiple databases to determine its significance in cancer prognosis, progression, staging, diagnosis, and treatment." (PMID 40129060, 2025). "Our study sought to fill this gap by systematically evaluating the predictive value of EPHX2 in pan‐cancer using multiple bioinformatic approaches." (PMID 40129060, 2025). "Comprehensive pan‐cancer analyses evaluating EPHX2's prognostic significance and biological functions across various tumors are limited." (PMID 40129060, 2025). "Further experimental validation, including in vitro and in vivo functional studies, is essential to confirm our findings and advance our understanding of EPHX2's role in cancer." (PMID 40129060, 2025). "Genomic research has revealed that deletion is the most common gene alteration of EPHX2 in most cancers." (PMID 40129060, 2025). "Single‐cell sequencing and GSVA highlighted the relevance of EPHX2 in regulating various cancer‐related biological processes, including cell cycle and apoptosis." (PMID 40129060, 2025). "Subsequently, we investigated the prognostic significance of EPHX2 in cancer patients by utilizing several databases." (PMID 40129060, 2025). "In this report, we systematically addressed the potential role of EPHX2 as a viable immunotherapy target in the TME against cancers." (PMID 40129060, 2025). "Despite its high predictive significance across cancers, EPHX2 played a protective or detrimental effect in distinct types of cancers." (PMID 40129060, 2025). "Considering that DNA methylation can silence gene expression, we analyzed the relationship of EPHX2 expression with DNA methylation across various cancers." (PMID 40129060, 2025). "EPHX2 encodes a cytosolic epoxide hydrolase, and its depletion in various cancers may induce aberrant expression, resulting in metabolic dysfunctions that could influence cancer progression and metastasis differently depending on the stage of cancer development." (PMID 40129060, 2025). "To ensure the robustness of our findings, we performed quantitative real‐time polymerase chain reaction (qRT‐PCR) experiments to confirm EPHX2 gene expression levels in various cancer cell lines." (PMID 40129060, 2025). "Genes often found to be epigenetically silenced or with low expression levels in ovarian or other cancers (Adora1, Bmp3, Ccl6, Ephx2, Lefty2, Pf4, Socs2) were downregulated by MOSE-LTICv in the OFB." (PMID 38264656, 2023).
cancer (continued). "Furthermore, we experimentally validated EPHX2 mRNA expression differences between cancer and normal cell lines." (PMID 40129060, 2025). "Following that, the GSVA analysis results demonstrated that EPHX2 could influence the occurrence and development of diseases such as cancers via multiple distinct signaling pathways." (PMID 40129060, 2025). "Despite these insights, most studies have focused on EPHX2's role in specific cancer types." (PMID 40129060, 2025). "EPHX2 may be a valuable biomarker for predicting responses to immunotherapy and guiding individualized immunotherapy strategies for cancer patients." (PMID 40129060, 2025). "Initially, we assessed EPHX2 mRNA expression in pan‐cancer using the TIMER2 method." (PMID 40129060, 2025). "Furthermore, the associations of EPHX2 with TMB, MSI, MMR genes, and ICPs were investigated across diverse cancer types." (PMID 40129060, 2025). "In DLBC, THYM, and THCA, EPHX2 was inversely correlated with TMB and MSI, suggesting that EPHX2 might indirectly affect the immunotherapy response in these cancers." (PMID 40129060, 2025). "EPHX2 may serve as a potential molecular biomarker for diagnosis and prognosis in pan‐cancer and could become a novel therapeutic target for various cancers." (PMID 40129060, 2025). "Abnormal EPHX2 expression has been observed in various cancers." (PMID 40129060, 2025). "Taken together, these results imply that EPHX2 could play either suppressor or oncogene roles, depending on the cancer type." (PMID 39125591, 2024). "Furthermore, EPHX2 expression was also validated by qPCR experiments in various cancer cell lines." (PMID 40129060, 2025). "EPHX2 expression correlated significantly and strongly with MMR gene expression in all 33 cancer types (excluding CHOL, DLBC, LAML, and PAAD)." (PMID 40129060, 2025). "Immunohistochemistry results from the HPA database demonstrated that EPHX2 was similarly expressed in most cancer types compared to normal tissues, aligning with mRNA expression profiles in the TCGA dataset, such as in PAAD, STAD, and BLCA." (PMID 40129060, 2025). "Remarkably, there are no clinical trials on EPHX2 focused on cancer, despite its potential role in inflammation-driven tumorigenesis." (PMID 39125591, 2024). "However, a recent study reveals that pharmacological inhibition of EPHX2, as well as dietary w-3 PUFA supplementation in different murine cancer models, can improve cancer immunotherapy against immune checkpoints such as PD-1 and CTLA." (PMID 39125591, 2024). "Although the beneficial effects of EPHX2 inhibitors on cancer patients have not been described yet, studies in animal models conducted by Dr. Hammock’s group have shown promising results." (PMID 39125591, 2024). "EPHX2, ACSF2, CYP27A1, ACSS1, and ALDH1L1 showed hypermethylation in several types of human cancer; on the contrary, AKR1B10, POLG2, NDUFB8, ACACB, and MRPS22 consistently showed hypomethylation in several types of human cancer." (PMID 37223030, 2023). "Moreover, EPHX2 expression exhibited the strongest positive correlation with CNA in PRAD, READ, and OV, indicating that CNA significantly impacts EPHX2 expression in these cancers." (PMID 40129060, 2025).
renal diseases (21 papers, 2010 to 2024). "The expression and activity of sEH have been reported to be associated with kidney diseases 32, and Ephx2 genetic deletion and chemical inhibition of sEH both attenuate renal diseases 32-34." (PMID 36594097, 2023). "In this review, we first clearly introduce the relationship between sEH and Epoxyeicosatrienoic acids (EETs), enumerate common typical EPHX2 single nucleotide polymorphisms (SNPs) associated with renal diseases and investigate the sEH-regulated potential mechanisms." (PMID 38425758, 2024). "Recently, the expression and activity of sEH have been reported in connection with kidney diseases 32, and Ephx2 genetic deletion and inhibition of sEH both attenuate renal diseases 32-34." (PMID 36594097, 2023).
metabolic disease (19 papers, 2017 to 2026). A congenital disorder (due to inherited enzyme abnormality) or acquired (due to failure of a metabolically important organ) disorder resulting from an abnormal metabolic process. "For metabolic diseases, EPHX2 may be a potential therapeutic target." (PMID 36176391, 2022).
neurological disorders (12 papers, 2019 to 2025). "Some genes, such as CD2AP, FCER1G, MAPK3, and EPHX2, were in nodes or core nodes of this neurological disease network, indicating that the CpG sites and these target genes may influence AD development." (PMID 38092781, 2023). "Ephx2 codes soluble epoxide hydrolase (sEH) and plays a key inflammatory role in metabolism of polyunsaturated fatty acids, thus regulating the pathogenesis of neurological diseases." (PMID 34347369, 2021).
inflammation (10 papers, 2014 to 2026). Aberrant reaction of the microcirculation characterized by movement of fluid and leukocytes from the blood into extravascular tissues. "Common upregulated genes were e.g. important for T cell immunobiology (ARG2, SLC43A2, IGFLR1), involved in cell migration (LAYN) or known to be involved in cigarette smoke-induced pulmonary inflammation and autophagy in mice (EPHX2)." (PMID 39052598, 2024). "Silencing of the EPHX2 gene in mice has been shown to attenuate renal inflammation and albuminuria, whereas experimental and clinical data have shown that epoxyeicosatrienoic acids and genetic variations of the EPHX2 gene were directly associated with insulin sensitivity and glucose homeostasis." (PMID 34040693, 2021).
blood cancer (1 paper, 2025). "Furthermore, PrognoScan GEO datasets revealed that EPHX2 was oncogenic in blood cancer and protective in colorectal, eye, lung, prostate, and soft tissue cancers." (PMID 40129060, 2025).